STOM (stomatin)
Description:
Regulates ion channel activity and transmembrane ion transport. Regulates ASIC2 and ASIC3 channel activity.
Synonyms: BND7; EPB72; EPB7
Tractability: Antibody: UniProt places it where antibodies can reach, with high confidence; its Gene Ontology location is reachable by antibodies, with high confidence; the Human Protein Atlas places it where antibodies can reach. PROTAC: ubiquitination databases record sites on it; its protein half-life has been measured.
Gene: Protein-coding gene on chromosome 9 (121,338,987 to 121,370,304, reverse strand). Ensembl gene ENSG00000148175.
Subcellular location: Cell membrane; Cytoplasm, cytoskeleton; Membrane raft; Melanosome; Cytoplasmic vesicle
Subcellular location (Human Protein Atlas): Plasma membrane; Vesicles; Cytosol
Pathways (Reactome):
Signal Transduction: CDC42 GTPase cycle; RHOA GTPase cycle; RHOB GTPase cycle; RHOC GTPase cycle; RHOH GTPase cycle; RHOJ GTPase cycle; RHOQ GTPase cycle
Immune System: Neutrophil degranulation
Transport of small molecules: Stimuli-sensing channels
Gene Ontology:
Molecular function: identical protein binding; protein binding; RNA polymerase binding; ion channel inhibitor activity; protein homodimerization activity
Biological process: host-mediated activation of viral genome replication; positive regulation of protein targeting to membrane; positive regulation of viral process; regulation of monoatomic ion transmembrane transport
Cellular component: blood microparticle; cytoskeleton; endoplasmic reticulum; extracellular exosome; extracellular region; melanosome; membrane; membrane raft; mitochondrion; plasma membrane; vesicle; azurophil granule membrane; cytoplasmic vesicle; specific granule membrane; tertiary granule membrane; cytoplasm; perinuclear region of cytoplasm
Genetic constraint (gnomAD): Loss-of-function variants: 18 observed, 23.7 expected, observed/expected ratio (o/e) 0.76, 90% interval 0.52 to 1.13. The upper end of that interval is the gene's LOEUF score, 1.13, which puts it in group 4 of 6, group 1 being the genes least tolerant of losing a copy. Missense variants: 244 observed, 311.93 expected, observed/expected ratio (o/e) 0.78, 90% interval 0.7 to 0.87. Synonymous variants: 102 observed, 115.72 expected, observed/expected ratio (o/e) 0.88, 90% interval 0.75 to 1.04.
Homologues: Orthologues: chimpanzee STOM (100% identical), macaque STOM (99% identical), pig STOM (94% identical), rabbit STOM (93% identical), guinea pig STOM (91% identical), rat Stom (88% identical), mouse Stom (86% identical), tropical clawed frog stom (81% identical), dog STOM (65% identical), Drosophila melanogaster CG42540 (62% identical), Caenorhabditis elegans sto-2 (61% identical). Paralogues in human: STOML3 (65% identical), NPHS2 (47% identical), STOML1 (31% identical), STOML2 (27% identical).
Diseases named in the same sentence as STOM in open-access papers:
STOM is named in the same sentence as 43 diseases in open-access papers, as found by Europe PMC text mining. Sharing a sentence is not in itself a finding about the gene and the disease. The quoted sentences say what the papers report.
breast carcinoma (4 papers, 2016 to 2025). "In breast cancer, several studies suggest that reduced stomatin expression may be linked to poorer prognosis." (PMID 40485728, 2025). "STOM encodes a major lipid-raft protein stomatin, which locates at the plasma membrane of multiple cell types, and is associated with non-small cell lung cancer and erb-b2 receptor tyrosine kinase 2-positive breast cancer." (PMID 29237456, 2017). "Our findings suggest stomatin as one potential prognostic factor that predicts the progression in HER2-positive breast cancer." (PMID 27577936, 2016). "Further studies investigating the mechanism whereby stomatin affects HER2-positive breast cancer and how stomatin interacts with HER2 are needed." (PMID 27577936, 2016). "Although stomatin is expressed in a significant proportion of breast cancers, the relationship between stomatin expression and breast cancer has not been explored in detail." (PMID 27577936, 2016). "Stomatin is the major component of lipid raft where HER2 is known to be clustered and therefore it seems likely that stomatin expression may have an impact on the pathology of HER2-positive breast cancer." (PMID 27577936, 2016). "Although hormonal receptors expression, cancer stage, and adjuvant trastuzumab therapy were all known prognostic factors for HER2-positive breast cancer, multivariate analyses revealed stomatin was an independent factor for cancer metastases (p = 0.017) for stage I-III HER2-positive breast cancers." (PMID 27577936, 2016). "It was found that negative stomatin expression was associated with a decreased breast cancer-specific survival and disease-free survival using survival analyses." (PMID 27577936, 2016). "One reason why previous researchers may have overlooked the relationship between stomatin and carcinogenesis may be because only a subgroup of breast cancers, namely the HER2-positive cancers, is affected by stomatin expression." (PMID 27577936, 2016). "For stage I-III HER2-positive breast cancer, the absence of stomatin expression was associated with a decreased 5-year disease-free survival (57 % vs. 81 %, p = 0.016) and was an independent prognostic factor by multivariate analysis." (PMID 27577936, 2016). "In our study, we initially proposed that lipid-raft localized stomatin might be able to modulate the activity of the HER2-positive breast cancer." (PMID 27577936, 2016). "In a total of 68 clinical cases of HER2-positive breast cancer, the absence of stomatin expression was associated with a decreased 5-year survival (65 % vs. 93 %, p = 0.005) by survival analysis." (PMID 27577936, 2016). "In the present study, the relationship of stomatin expression and the clinical survival outcome was explored for patients with HER2-positive breast cancer." (PMID 27577936, 2016). "The present study provides evidence showing a correlation between stomatin protein expression and HER2-positive breast cancer prognosis." (PMID 27577936, 2016). "In contrast, in breast cancer, the expression of stomatin in these cells was 31 % (7/23) negative, 39 % weak (9/23), 26 % moderate (6/23), and 4 % (1/23) strong positive when tissue microarrays were analyzed by immunohistochemistry." (PMID 27577936, 2016). "In women of HER2-negative cancers, the 5-year breast cancer-specific survival rates were 84 % (95 % confidence interval = 67 to 92 %) for women of positive stomatin expression and 94 % for women of negative stomatin expression (95 % confidence interval = 67 to 99 %, p = 0.193)." (PMID 27577936, 2016). "Kaplan-Meier plot showed that the 5-year breast cancer-specific survival rates were 93 % (95 % confidence interval = 76 to 98 %) for women of positive stomatin expression and 65 % for women of negative stomatin expression (95 % confidence interval = 38 to 83 %, p = 0.005)." (PMID 27577936, 2016). "The results that absence of stomatin expression might predict distant metastases in HER2-positive breast cancer are comparable to that of Arkhipova’s study for lung cancer." (PMID 27577936, 2016).
Sepsis (4 papers, 2017 to 2025). Sepsis is defined as life-threatening organ dysfunction caused by a dysregulated host response to infection. "Among those novel hub genes, we assessed the expression patterns of MYBL1, KLRG1, STOM and MS4A4A from the top 2 sepsis-associated modules (module “midnight blue” and module “cyan”) by qPCR." (PMID 29237456, 2017). "In this study, ROC analysis results further indicate that the four hub genes (MYBL1, KLRG1, STOM and MS4A4A) had good diagnostic performance in sepsis, close to that of genes previously reported." (PMID 29237456, 2017). "Both the qPCR results and ROC analysis results suggest that the four hub genes (MYBL1, KLRG1, STOM and MS4A4A) could be novel diagnostic biomarkers for pediatric sepsis." (PMID 29237456, 2017). "For example, the outgoing signaling of C1_CD36, C3_B, C9_STOM, and C10_ULK1 cells was dominated by “pattern 1,” which included RESISTIN and VISFATIN in sepsis." (PMID 37919720, 2023). "qPCR results suggest hub genes (MYBL1, KLRG1, STOM and MS4A4A) in the candidate modules as promising potential transcriptomic markers for pediatric sepsis diagnosis." (PMID 29237456, 2017). "While STOM and MS4A4A were significantly overexpressed in sepsis samples, compared with controls (P = 0.04 and P < 0.001 respectively)." (PMID 29237456, 2017). "STOM was highly expressed in platelet subpopulations in the normal and Sepsis groups, while CLFAR expression was higher in the monocyte subpopulation, neutrophil subpopulation, and NK cell subpopulations in the Sepsis group compared to the normal group." (PMID 37007944, 2023).
cryohydrocytosis (3 papers, 2018 to 2022). A rare, hereditary, hemolytic anemia due to a red cell membrane anomaly characterized by fatigue, mild anemia and pseudohyperkalemia due to a potassium leak from the red blood cells. "One patient with a positive finding was prescribed a new ketogenic diet to reduce seizures based on the diagnosis of neurologic defects with stomatin‐deficient cryohydrocytosis (OMIM#138140)." (PMID 30318729, 2018). "South-east Asian Ovalocytosis (SAO), cryohydrocytosis (CHC) and stomatin-deficient CHC (sdCHC) have an intermediate cation leak (4-10x normal) and MCVs between 100-120fL." (PMID 35356079, 2022). "These conditions include dehydrated hereditary stomatocytosis (DHSt) and overhydrated hereditary stomatocytosis (OHSt), familial pseudohyperkalaemia (FP), cryohydrocytosis (CHC), stomatin-deficient cryohydrocytosis (sdCHC) and South-east Asian Ovalocytosis (SAO)." (PMID 35323786, 2022).
hereditary stomatocytosis (3 papers, 2013 to 2022). "In a form of hemolytic anemia known as hereditary stomatocytosis, stomatin is deficient in the erythrocyte membrane due to mis-trafficking." (PMID 36386441, 2022). "In a form of hemolytic anemia known as hereditary stomatocytosis, the stomatin protein is deficient in the erythrocyte membrane due to mis-trafficking." (PMID 36386441, 2022). "In a form of human hemolytic anemia known as hereditary stomatocytosis, the stomatin protein is deficient in the erythrocyte membrane due to mis-trafficking." (PMID 24121343, 2013). "The monomeric form of stomatin, also known as protein 7.2 or as the major component of band 7, exhibits an apparent molecular weight of 31-kDa and is totally absent from mature RBCs of a rare human haemolytic anaemia, hereditary stomatocytosis (OHSt)." (PMID 36012667, 2022).
lung carcinoma (3 papers, 2014 to 2018). "Our data indicate that decreased stomatin expression is an unfavorable factor for lung cancer; however, the mechanisms of its action are unclear." (PMID 24533441, 2014).
non-small cell lung carcinoma (3 papers, 2014 to 2018). A group of at least three distinct histological types of lung cancer, including non-small cell squamous cell carcinoma, adenocarcinoma, and large cell carcinoma. "We performed a correlation analysis of caveolin-1, stomatin, and flotillin-1 mRNA expression in the whole group of non-small cell lung cancer (NSCLC) specimens and in its subgroups in accordance with the clinicopathological characteristics of the specimens." (PMID 24533441, 2014). "At the present time, there is a lack of data about the involvement of flotillins and stomatin in the development of non-small cell lung cancer (NSCLC) and soft tissue sarcomas (STS)." (PMID 24533441, 2014).
anemia (2 papers, 2018 to 2024). A reduction in the number of red blood cells, the amount of hemoglobin, and/or the volume of packed red blood cells. "Finally, another highly desirable candidate, STOM, encodes an integral membrane protein that localizes to red blood cells, the loss of which has been linked to anemia." (PMID 30453955, 2018).
cervical cancer (2 papers, 2022 to 2023). A primary or metastatic malignant neoplasm involving the cervix. "Additionally, concurrently with the patient data, transcriptome and proteomic profiling of Caspase-8-depleted cervical cancer cell lines (HeLa and SiHa) identified numerous genes with altered expression, including STOM and TGM2, which may boost the propensity for metastasis and invasion." (PMID 36399280, 2022).
ovarian carcinoma (2 papers, 2022 to 2023). A malignant neoplasm originating from the surface ovarian epithelium. "In our previous study, we first showed the presence of stomatin in exosomes produced by epithelial cancer cells (lung, breast and ovarian cancer cells) as well as in EVs from various body fluids, including blood plasma, ascitic fluid and uterine flushes." (PMID 35884376, 2022).
B-cell lymphoma (1 paper, 2025). "We also found that stomatin expression is lower in orbital tumor tissues of patients with other types of B-cell lymphoma, suggesting its high specificity in orbital DLBCL." (PMID 40485728, 2025).
glioma (1 paper, 2021). A benign or malignant brain and spinal cord tumor that arises from glial cells (astrocytes, oligodendrocytes, ependymal cells). "In glioma grade IV, highly activated DEGs included STOM, IGHG4, CXCL13, MMP13, and CAPN6, while highly downregulated DEGs included JAZF1-AS1 and ELDR." (PMID 33948562, 2021).
infiltrating ductal carcinoma (1 paper, 2016). "Using 68 HER2-positive and 58 HER2-negative samples of infiltrating ductal carcinomas of the female breast, stomatin protein expression was found to be localized mainly in the plasma membrane and partially in the cytosol." (PMID 27577936, 2016). "In our preliminary study for the histologies other than infiltrating ductal carcinoma, we can not make any conclusion in the influence of stomatin expression to cancer outcomes because the sample size is too small." (PMID 27577936, 2016).
inflammatory skin disease (1 paper, 2024). Inflammatory skin disorders covers a broad category that includes many conditions ranging in severity, from mild itching to grave medical health complications These disorders are common in people of all ages and races. "Among other genes related to the immune system are TRIM32 or STOM, and altered innate immunity is a feature of certain inflammatory skin diseases." (PMID 39199954, 2024).
Insulin resistance (1 paper, 2022). Increased resistance towards insulin, that is, diminished effectiveness of insulin in reducing blood glucose levels. "Stomatin transgenic mice fed with high-fat diet exhibit obesity, insulin resistance and hepatic impairments; however, such phenotypes are not seen in transgenic animals fed with regular diet." (PMID 35854007, 2022).
lung adenocarcinoma (1 paper, 2018). A carcinoma that arises from the lung and is characterized by the presence of malignant glandular epithelial cells. "Moreover, we collected four tissue samples of surgically removed lung adenocarcinoma and their paired normal adjacent tissue to evaluate the protein level of STOM and TPM4." (PMID 30348215, 2018). "SUV39H2 could potentiate the tumorigenesis and invasion of lung adenocarcinoma cells, probably by repressing OPTN and STOM." (PMID 30348215, 2018).
malignant fibrous histiocytoma (1 paper, 2014). "However, such up-regulation is more typical for malignant fibrous histiocytoma, one of the most aggressive types of STS, where out of 7 studied specimens only in one case stomatin mRNA levels were equal in normal and tumor tissues." (PMID 24533441, 2014).
MALT lymphoma (1 paper, 2025). An indolent, extranodal type of non-Hodgkin lymphoma composed of small B-lymphocytes (centrocyte-like cells). "The expression of stomatin mRNA and protein in orbital tumor tissue of patients with orbital DLBCL was significantly higher than that of orbital MALT lymphoma and orbital follicular lymphoma (P<0.05)." (PMID 40485728, 2025).
nephrotic syndrome (1 paper, 2025). A collection of symptoms that include severe edema, proteinuria, and hypoalbuminemia; it is indicative of renal dysfunction. "For example, several disease-causing mutations in Podocin33,35,36—linked to nephrotic syndrome—occur at key structural sites in our Stomatin model." (PMID 40796562, 2025).
Obesity (1 paper, 2022). Accumulation of substantial excess body fat. "The finding that stomatin regulates fatty acid uptake and LD growth may provide new opportunities for correcting whole-body energy disorders or energy surplus-induced obesity by modulating the molecular events associated with stomatin." (PMID 35854007, 2022). "The high amount of stomatin in adipose tissues raises the possibility that stomatin may play important roles in the development and function of adipocytes, and that dysfunction of stomatin-mediated regulations on adipogenesis may lead to lipid metabolisms-associated disorders, such as obesity." (PMID 35854007, 2022). "The calculated heat production during the light-dark cycle was slightly higher in HFD-fed STOM Tg mice than in controls, thus could not be accounted for the observed obesity phenotype." (PMID 35854007, 2022).
osteosarcoma (1 paper, 2025). A usually aggressive malignant bone-forming mesenchymal neoplasm, predominantly affecting adolescents and young adults. "This study identifies EPYC, CLDN11, and STOM for the first time as biomarkers associated with the prognosis of osteosarcoma." (PMID 40075313, 2025). "The five biomarkers (CD36, CLDN11, EPYC, PANX3, and STOM) were screened to construct an AAMRGs risk model with prognostic value, providing a new reference for the prognosis and treatment of osteosarcoma." (PMID 40075313, 2025). "The roles of PANX3 and CD36 are well established; however, the specific functions of EPYC, CLDN11, and STOM in osteosarcoma remain unclear." (PMID 40075313, 2025). "In addition, CD36, CLDN11 and STOM were found to have lower expression between osteosarcoma tissue samples compared to para-carcinoma tissue." (PMID 40075313, 2025). "Validation of gene expression through public databases and RT-qPCR results showed significant upregulation of EPYC and PANX3 in osteosarcoma samples, while CD36, CLDN11, and STOM were significantly downregulated." (PMID 40075313, 2025). "The differential analysis showed that in the osteosarcoma group, the expression of EPYC and PANX3 was obviously elevated, whereas the expression of CD36, CLDN11 and STOM was markedly decreased." (PMID 40075313, 2025). "In order to develop a risk model with the optimal prognostic predictive capacity of these DE-AAMRGs in osteosarcoma patients, we performed univariate Cox analysis and utilized the LASSO method to select a panel of five biomarkers (CD36, CLDN11, EPYC, PANX3, and STOM)." (PMID 40075313, 2025).
prostate carcinoma (1 paper, 2024). A carcinoma that arises from epithelial cells of the prostate gland. "Cell-to-cell contact of prostate cancer cells through the EphA-ephrin-A interaction suppressed stomatin expression, while knockdown of EphA3/7 or ephrin-A5 increased stomatin expression." (PMID 39377541, 2024).
sickle cell disease (1 paper, 2021). Sickle cell anemias are chronic hemolytic diseases that may induce three types of acute accidents: severe anemia, severe bacterial infections, and ischemic vasoocclusive accidents (VOA) caused by sickle-shaped red blood cells obstructing small blood vessels and capillaries. "Moreover, the proteasome-enriched membrane of sickle cell disease RBCs has been characterized by decreased levels of RBC raft-resident flotillins and stomatin." (PMID 34564533, 2021).
soft tissue sarcoma (1 paper, 2014). A malignant neoplasm arising from muscle tissue, adipose tissue, blood vessels, fibrous tissue, or other supportive tissues excluding the bones. "In this work, we demonstrated for the first time that stomatin mRNA and protein expression changes in tumor specimens of patients with NSCLC and soft tissue sarcomas." (PMID 24533441, 2014).
squamous cell carcinoma (1 paper, 2014). A carcinoma arising from squamous epithelial cells. "We investigated the mRNA expression of flotillin-1, stomatin, and caveolin-1 using real-time PCR in 22 paired (tumor and corresponding normal tissue) samples of adenocarcinomas and 26 paired samples of squamous cell carcinomas." (PMID 24533441, 2014).